FADD (Fas associated via death domain)
Diseases named in the same sentence as FADD in open-access papers (continued):
Sharing a sentence is not in itself a finding about the gene and the disease.
tumor (continued). "Knock down of the toxic BH3 domain protein BID, which is downstream of CD95, FADD and pro-caspase 8, significantly reduced the ability of regorafenib alone or in combination with aramchol to cause autophagosome and autolysosome formation and to kill tumor cells." (PMID 40827882, 2025). "Furthermore, posttranslational modifications of FADD, especially phosphorylation and ubiquitination, may underlie the alterations of FADD functions in tumor cells." (PMID 31569512, 2019). "The results presented in this study indicate that FOXO1 has a tumor suppressor function, while FADD has a tumor-promoting function in OS following anticancer drug treatment." (PMID 41596582, 2026). "The reduction in autophagosome formation observed when CD95 or FADD was knocked down was mirrored in the ability of CD95 or FADD to kill tumor cells." (PMID 40827882, 2025). "In OVCAR-3 cells, both FasLMem. and FasLS clustered Fas and FADD, while in HbMEC cells, both soluble FasLS and FasLST partly clustered Fas and FADD (although at much lower levels than tumor cells)." (PMID 40593750, 2025). "We have previously demonstrated that FADD can effectively target the anti-apoptotic protein cFLIP and the pro-inflammatory NF-κB pathway in various tumor cell types, highlighting the potential of FADD as a therapeutic candidate." (PMID 38542202, 2024). "The heterogeneous expression of FADD and cFLIP across different tumor types confers resistance to death receptor-induced apoptosis." (PMID 38542202, 2024). "By CCK8 assay, we confirmed that FADD played a role in promoting tumor cell proliferation in LUAD cell lines." (PMID 37671047, 2023). "FADD and KIAA family-related genes were also implicated in tumor progression, while SMN1 showed connections to immune function and poor prognosis in related tumors." (PMID 37760507, 2023). "Further analysis revealed a significant increase in angiogenic, EMT, and hypoxic pathway activity in patients with high FADD, which represents a positive correlation between high FADD and the malignant features of the tumor." (PMID 37671047, 2023). "According to the gene ontology analysis in this study, FADD can initiate anti-tumor necroptosis and aid the process of T cell-mediated cytotoxicity." (PMID 36732815, 2023). "Notably, higher FADD expression is positively associated with increased infiltration of suppressive immune cells (Tregs and M2 macrophages), which may lead to suppressed antitumor activity and immune escape of active tumor cells in patients with high FADD." (PMID 37671047, 2023). "As assessed by the ESTIMATE algorithm, low FADD subtypes had higher immune scores, while high FADD subtypes had higher tumor purity." (PMID 37671047, 2023). "Our GSEA suggests that tumor cell cycle pathways are enriched and cell proliferation is active in high FADD, and the active cell cycle provides more targets for conventional chemotherapeutic agents, thus leading to greater sensitivity to chemotherapy." (PMID 37671047, 2023). "The tumor-targeted delivery of FADD or truncated FADD inhibited tumor growth by inducing apoptosis of tumor cells via activating caspase-dependent apoptotic pathway." (PMID 36348274, 2022). "To confirm the participation of FADD in energy metabolism, we studied the interactome of endogenous FADD in tumor T-cells." (PMID 36499482, 2022). "Reduction of FADD phosphorylation that inversely correlates with the proliferation capacity and tumor aggressiveness." (PMID 36348274, 2022). "Excepted for being related to apoptosis, FADD is also involved in the process of cell cycle progression, proliferation, innate immunity, tumor development, inflammation, and autophagy." (PMID 34423028, 2021). "Further screening for proteins related to the tumor chemotherapy sensitivity, inspiringly, gene FADD and its role-related genes RIPK1, found that FADD in the Ca group was highly expressed, and RIPK1 was poorly expressed in the Ca group." (PMID 34262870, 2021).
tumor (continued). "In HNSCC cell lines, FADD expression was higher in HPV(−) tumor lines, and TNFRSF10A/B/C exhibited decreased expression in HNSCC compared to normal human oral keratinocyte lines (HOK)." (PMID 33737574, 2021). "Otherwise, several researches have reported that FADD, the key adaptor protein in the apoptosis signaling pathway, was correlated with both tumor aggressiveness and tumor progression." (PMID 34630090, 2021). "As a combination of RIPK1 and FADD, the FADDosome has emerged as an important factor in autophagy, tumor growth promotion, and resistance to chemotherapy." (PMID 34262870, 2021). "Secondly, tumor cells can sabotage apoptotic signal in many different levels by increasing cFLIP, reducing FADD expression, and attenuating caspase-8 expression." (PMID 32212814, 2020). "To minimize this limitation, we made an estimation through the performance of an albatross plot, which showed an association between FADD overexpression and perineural invasion, which may constitute one more justification for the relationship between FADD and metastatic development in these tumours." (PMID 32847023, 2020). "FADD is originally described as an adapter molecule mediating apoptosis, which has been newly revealed to engage in cell survival and tumor development." (PMID 33456497, 2020). "In this current study, VNP-FADD induced the overexpression of FADD in tumour tissues, which was further increased after ADT-OH treatment." (PMID 31949127, 2020). "As expected, FADD preferentially accumulated in the necrotic area of the tumour, indicating that FADD was successfully and highly expressed in the tumour hypoxic region." (PMID 31949127, 2020). "The IHC staining of tumor slides from xenograft models also confirmed a higher level of FADD expression in ATRX KO group compared to the ATRX NC group." (PMID 32194873, 2020). "All of these results indicate that FADD overexpression combined with ADT-OH treatment exhibits excellent tumour suppression effects with little side effects." (PMID 31949127, 2020). "The role of FADD in apoptosis is controversial; some studies have reported an anti-apoptotic effect and others a pro-apoptotic action in tumor cells." (PMID 31741709, 2019). "Our group has reported a reduction of FADD together with reduced apoptosis in T-LBL samples, but the accumulation of phosphorylated FADD in the nuclei of tumor cells." (PMID 31569512, 2019). "For example, it has been reported that overexpressing FADD in colorectal cancer or malignant glioma renders tumor cells more sensitive to apoptosis, thus improving the effect of chemotherapy." (PMID 31569512, 2019). "Ablation of NRF1 degradation enhances tumor cell apoptosis in a FADD-dependent manner, which induces secondary necrosis due to insufficient clearance of the apoptotic cell caused by the lack of polarized TAMs." (PMID 30833558, 2019). "In summary, E3-ubiquitin ligases constitute a potential therapeutic target with regards to FADD availability and function in the tumor cell." (PMID 31569512, 2019). "Orthotopic implanted TRAIL resistant A549 NSCLC and murine LL3 cells with FADD deleted showed reduced tumor growth compared to implanted WT tumor cells." (PMID 31333662, 2019). "Posttranslational modifications also constitute a relevant mechanism controlling FADD levels and functions in tumor cells." (PMID 31569512, 2019). "A variety of FADD protein levels can be observed across the different tumor types; the mechanisms responsible for altered expression are, however, not always elucidated." (PMID 31569512, 2019). "Considering that the knockdown of BRCA1 caused reduction of the FADD level, we suggest that the loss of BRCA1 (or its inactivation) in a tumor can cause reduced levels of FADD that in turn desensitizes cells to a FasL-mediated anti-proliferative effect." (PMID 29757984, 2018).
tumor (continued). "In line with our results implicating FADD as crucial for TRAIL-R-mediated CCL2 secretion, 3LL FADD KO cells replicated our results observed in CCR2 KO mice regarding tumor burden and myeloid infiltrates." (PMID 28212753, 2017). "So far, our results established FADD presence in tumor cells as a significant driver of both in vivo cytokine production and the presence of alternatively activated myeloid cells." (PMID 28212753, 2017). "TUNEL assays showed that the antitumor effects of FADD or N-FADD were mainly mediated through evoking and enhancing apoptosis of tumor cells." (PMID 27767039, 2016). "Briefly, using this strategy, we successfully make tumor-specific delivery of FADD and N-FADD proteins." (PMID 27767039, 2016). "According to this model, tumor cells within the window between the two thresholds (Moderate T-LBLs) would lack proper FADD-involved apoptosis, but would be competent for FADD-mediated proliferation, cell cycle and/or survival, thus becoming more aggressive." (PMID 27556297, 2016). "It has been postulated that, in those many studies in which tumor progression has been shown to correlate with reduced FADD or phospho-FADD, the apoptotic role of FADD is stressed, and thus is FADD regarded as a tumor suppressor gene." (PMID 27556297, 2016). "After adjusting for age at diagnosis, primary tumor status, lymph node status and tumor differentiation using multivariate analysis, patients with high FADD protein expression also showed a poorer DFS (HR = 1.575, 95% CI, 1.078–2.300)." (PMID 27764170, 2016). "FADD reduction has been also observed in tumor types like human non-small cell lung cancer, hepatocellular carcinoma or thyroid adenoma/adenocarcinoma." (PMID 27556297, 2016). "Upstream regulators of the tumor-associated mouse genes significantly altered by metronomic CPA treatment include DDX58, as well as FADD and MAVS." (PMID 25952672, 2015). "Collectively, AK2 appears to be a strategic controller that acts to coordinate both cell proliferation and FADD dephosphorylation in these tumour cells." (PMID 24548998, 2014). "As shown, the frequency of methylation status for FADD gene was 12.79 % in tumor tissues (11 of 86 cases) and zero for normal mucosa." (PMID 25129245, 2014). "The ability of AK2 to regulate FADD phosphorylation was also observed in Chang liver and Huh-7 tumour cells." (PMID 24548998, 2014). "miR-27a was found to function as a tumor suppressor by targeting the anti-apoptotic protein FADD in human embryonic kidney cells." (PMID 23229173, 2013). "Combination treatment of TMZ with pG8-FasL/FADD significantly prolonged the survival of the tumor-bearing mice in comparison to TMZ or pG8-FasL/FADD alone." (PMID 20942909, 2010). "As expected, co-expression of both FasL and FADD prolonged the median survival time of ΔGli36 tumor-bearing mice." (PMID 20942909, 2010). "Despite these variable parameters, pG8-FasL/FADD amplicon viruses can still mediate a suppressive effect on the tumor growth." (PMID 20942909, 2010). "Complete tumor regression was observed in animals injected with pG8-FasL/FADD followed by combined treatment with TMZ and IR." (PMID 20942909, 2010). "Tumors exhibiting high staining intensity were classified as potentially over-expressing, with 70 out of 258 (27.1%) and 51 out of 295 (17.3%) of tumor samples over-expressing cortactin and FADD, respectively." (PMID 18823530, 2008). "Involvement of FADD phosphorylation in cell cycle arrest has also been indicated in breast epithelial or tumour cells." (PMID 16450001, 2006). "Based on our autophagy data we determined whether the role of BID in tumor cell killing was due to canonical signaling from death receptor CD95/FADD though caspase 8 to cleave BID, or through a different mechanism." (PMID 40827882, 2025).
tumor (continued). "We can speculate that post-translational mechanisms may impact the maturation of RNA into protein in the metastatic tissue of responder patients, resulting in the modulation of tumor resistance pathways involving FADD and STAT2." (PMID 39273294, 2024). "Additionally, the injection of FADD knockout A549 cells in mice resulted in the development of lung tumors, highlighting the role of the TRAIL-FADD-NF-κB signaling axis in cytokine and tumor regulation." (PMID 38542202, 2024). "Dysregulated expression of FADD could serve as a prominent tumor biomarker and prognostic factor for developing appropriate treatment strategies." (PMID 38542202, 2024). "Notably, our results suggest that low FADD is associated with greater PD-1 and PD-L1 expression and that patients with low FADD have immune-active tumor microenvironments." (PMID 37671047, 2023). "The subtype with high FADD expression has a dysregulated cell cycle that may lead to active tumor cell replication and proliferation." (PMID 37671047, 2023). "For example, FADD is a risk factor, whereas TLR3 is a protective factor for most tumours." (PMID 36583248, 2023). "Conversely, deletion or decreased expression of FADD may lead to cellular resistance to apoptotic signaling, which can lead to tumor development and growth." (PMID 37671047, 2023). "FADD is involved in necroptosis, which aids in both tumor formation and suppression." (PMID 36732815, 2023). "In conclusion, these results suggest that patients with low FADD subtypes have a stronger oxidative stress response and immune activity, whereas tumor cells with high FADD subtypes have a dysregulated cell cycle with hyperactive cell division and cell proliferation." (PMID 37671047, 2023). "In these cases, restoring or increasing the expression of FADD may help restore sensitivity to apoptotic signals and stop further tumor development." (PMID 37671047, 2023). "Taken together, our results suggest that FADD represents different states of the “cold” and “hot” tumor microenvironment and may contribute to the heterogeneity of tumor treatment sensitivity." (PMID 37671047, 2023). "AFP also exerts a pro-oncogenic priming in both animal and human models of HCC by reducing the FAS/FAS-associated death domain protein (FADD) apoptotic pathway through the modulation of Human Antigen R RNA-binding protein, resulting in the promotion of tumor growth." (PMID 36230554, 2022). "Further studies of FADD interactions in patients may shed light on the molecular mechanisms whereby FADD can deregulate cellular signals in the tumor." (PMID 36499482, 2022). "We show that glutamine starvation triggers a FADD and caspase-8-dependent and mitochondria-operated apoptotic program in tumor cells that involves the pro-apoptotic TNF-related apoptosis-inducing ligand receptor 2 (TRAIL-R2), but is independent of its cognate ligand TRAIL." (PMID 36302756, 2022). "Notably, 8 autophagy-related genes (CAPN10, DAPK2, MBTPS2, ST13, CFLAR, FADD, PEX14 and TSC2) and 2 immune cells (Mast cells and Eosinophils) were revealed to be highly associated with tumor prognosis." (PMID 34093817, 2021). "We speculate that this could be due to the reduced number of tumor cells that express H19 and miR-675 or due to as yet unknown mechanisms that abrogate the degradation of FADD mRNA by miR-675." (PMID 33499244, 2021). "At the same time, it was also poorly expressed in chemotherapy-sensitive patients and highly expressed in chemotherapy-resistant patients, further indicating that FADD may play a role in tumor chemotherapy sensitivity." (PMID 34262870, 2021). "It was reported that apigenin and luteolin belong to flavonoids, that can inhibit the growth of intestinal adenoma cells by reducing the phosphorylation of AKT and up-regulating the expression of FADD, indicating that apigenin and luteolin can inhibit the invasion and metastasis of tumor cells." (PMID 33692692, 2021).
tumor (continued). "It has been hypothesized that the death receptor signalling pathway DR5/FADD/caspase-8 could promote the development of metastases mediated by tumour cells with acquired mechanisms of apoptosis resistance." (PMID 32847023, 2020). "In this context, few studies investigated the vector-based FADD gene therapy approach in regulation of tumor growth and apoptosis in synoviocytes; however, adenoviral or vector-based approaches have limited control over protein expression and host-derived factors." (PMID 32961826, 2020). "Clinical stage: A significant association was for among FADD upregulation and advanced stage tumours (OR = 1.74, 95% CI = 1.26–2.41, p = 0.001) with no observable heterogeneity (p = 0.44, I2 = 0.0)." (PMID 32847023, 2020). "Recent studies have indicated that FADD expression is correlated with tumor development." (PMID 33194633, 2020). "Similarly, high expression of FADD was observed in NSCLC, and it was considered to be associated with the increased invasive behavior of the tumor and a marker for predicting prognosis." (PMID 31938577, 2020). "Meta-analysis was not performed for the association between FADD upregulation and the additional variables (histological grade; local recurrence; tumour thickness; margins; extracapsular spread; and bone, skin, lymphatic, vascular and perineural invasion)." (PMID 32847023, 2020). "After activation, CTL expresses FasL and TNF-α, binds to the Fas and TNFR1 on the surface of tumor cells, and generates FADD, which will conduct the apoptosis signal into the cell and perform CASP8 proteolytic activation, thus initiating the apoptosis process of tumor cells." (PMID 31905767, 2019). "Chromosomal alterations affecting FADD are more frequent than mutations or polymorphisms, but they do not always explain the changes in expression observed in tumor cells." (PMID 31569512, 2019). "If FADD involvement in these functions is confirmed in humans, it could be speculated that the alterations in FADD observed in tumor cells may also impact on energy metabolism." (PMID 31569512, 2019). "Also, some chemotherapeutic agents—such as Carboplatin in tongue carcinoma or Nortriptyline in bladder cancer cells —induce the expression of FADD, thus contributing to tumor cell sensitization to apoptosis." (PMID 31569512, 2019). "Their data showed that this system (hTERT/FADD) could effectively induce the apoptosis of tumor cells and inhibit the growth of tumor cells in vivo." (PMID 29858085, 2018). "Therefore, TRAIL can trigger the secretion of myeloid cell-polarizing factors from tumor cells in a FADD-dependent manner." (PMID 28212753, 2017). "Importantly, this effect was recapitulated in a syngeneic model wherein deletion of murine FADD in two independent 3LL clones significantly impaired tumor growth, demonstrating a tumor-promoting role of FADD across species." (PMID 28212753, 2017). "Therefore, FADD presence promotes the growth of lung tumors, encourages the formation of a tumor-supportive cytokine milieu, and increases the accumulation of M2-like myeloid cells." (PMID 28212753, 2017). "In a recent study, we observed that 35% of human T-LBL cases exhibited reduced levels of Fas-associated death domain protein (FADD), suggesting that FADD reduction would be a frequent mechanism whereby FAS-mediated apoptotic signaling would be affected in this type of tumor." (PMID 27556297, 2016). "Notably, a considerable inter-tumor heterogeneity regarding FADD and – particularly - S191-P-FADD levels was observed among the T-LBL samples." (PMID 27556297, 2016). "With the help of microarray and qRT-PCR analysis, we predicted that miR-7a, a reported tumor suppressor miRNA which inhibits tumor migration and invasion, might be an indispensable player in the interplay between FADD and FAK." (PMID 27286445, 2016).